CUZD1 (CUB and zona pellucida like domains 1)
Description:
Localized to zymogen granules, where it functions in trypsinogen activation (By similarity). May indirectly regulate cell motility, cell-cell and cell/extracellular matrix interactions.
Synonyms: ERG-1; UO-44; ERG1; ITMAP1
Tractability: Antibody: UniProt predicts a signal peptide or a membrane-spanning region.
Gene: Protein-coding gene on chromosome 10 (122,832,158 to 122,846,175, reverse strand). Ensembl gene ENSG00000138161.
Subcellular location: Zymogen granule membrane
Gene Ontology:
Biological process: trypsinogen activation
Cellular component: membrane; cell surface; zymogen granule membrane; zymogen granule
Genetic constraint (gnomAD): Loss-of-function variants: 46 observed, 55.15 expected, observed/expected ratio (o/e) 0.83, 90% interval 0.66 to 1.07. The upper end of that interval is the gene's LOEUF score, 1.07, which puts it in group 4 of 6, group 1 being the genes least tolerant of losing a copy. Missense variants: 670 observed, 745.62 expected, observed/expected ratio (o/e) 0.9, 90% interval 0.84 to 0.96. Synonymous variants: 238 observed, 272.19 expected, observed/expected ratio (o/e) 0.87, 90% interval 0.79 to 0.97.
Homologues: Orthologues: chimpanzee CUZD1 (99% identical), macaque CUZD1 (96% identical), guinea pig CUZD1 (79% identical), dog CUZD1 (77% identical), rabbit CUZD1 (76% identical), rat Cuzd1 (74% identical), mouse Cuzd1 (71% identical). Paralogues in human: MFRP (16% identical), CNTNAP4 (13% identical), CNTNAP5 (12% identical), NRXN2 (12% identical), CNTNAP3 (12% identical), CNTNAP3B (12% identical), NRXN1 (12% identical), CNTNAP2 (11% identical), CUBN (11% identical), F5 (11% identical), F8 (11% identical), NRXN3 (11% identical), and 23 more.
Diseases named in the same sentence as CUZD1 in open-access papers:
CUZD1 is named in the same sentence as 16 diseases in open-access papers, as found by Europe PMC text mining. Sharing a sentence is not in itself a finding about the gene and the disease. The quoted sentences say what the papers report.
inflammatory bowel disease (4 papers, 2013 to 2023). A spectrum of small and large bowel inflammatory diseases of unknown etiology. "This group has also studied in some detail the diagnostic significance of anti-CUZD1 PABs in inflammatory bowel diseases." (PMID 23710207, 2013). "CUZD1 is specifically linked to inflammatory bowel disease (IBD), as autoantibodies elicited against it have been proposed as a novel serological biomarker of CD." (PMID 31249498, 2019). "There is little functional information with CUZD1 except for the fact that anti-CUZD1 antibodies are used as a marker of inflammatory bowel disease in humans." (PMID 27685470, 2016). "Serum samples from patients with inflammatory bowel disease (IBD) were analyzed by ELISA for the presence of autoantibodies to CUB and zona pellucida-like domain-containing protein 1 (CUZD1)." (PMID 31249498, 2019). "Currently, there are no data evaluating the clinical relevance of anti-CUZD1 antibodies in patients with inflammatory bowel diseases." (PMID 23710207, 2013). "CUZD1, the CUB, and zona pellucida-like domains-containing protein 1, is a newly identified antigen of pancreatic autoantibodies (PAB) giving a reticulogranular pattern in patients with inflammatory bowel diseases, and in particular Crohn's disease." (PMID 23710207, 2013).
Crohn disease (2 papers, 2013 to 2018). A gastrointestinal disorder characterized by chronic inflammation involving all layers of the intestinal wall, noncaseating granulomas affecting the intestinal wall and regional lymph nodes, and transmural fibrosis. "Both CUZD1 and GP2 are expressed in pancreatic tissue in humans and pancreatic autoantibodies targeting GP2 and CUZD1 are used as Crohn’s disease-markers." (PMID 29765364, 2018).
age-related macular degeneration (1 paper, 2021). Age-related loss of vision in the central portion of the retina (macula), secondary to retinal degeneration. "Single nucleotide polymorphisms (SNPs) in Cuzd1 have been associated with risk of age-related macular degeneration." (PMID 34440888, 2021).
autoimmune disease (1 paper, 2013). A disorder resulting from loss of function or tissue destruction of an organ or multiple organs, arising from humoral or cellular immune responses of the individual to their own tissue constituents. "CUZD1 appears to be one of the relatively few biomarkers that serve as both cancer biomarker and autoantigen of autoantibodies in an autoimmune disease unrelated to cancerous organs." (PMID 23710207, 2013).
Autoimmunity (1 paper, 2013). The occurrence of an immune reaction against the organism's own cells or tissues. "The de novo induction of anti-CUZD1 antibodies can be the end result of microbial-induced autoimmunity, similar to that possibly involved in the induction of GP2 autoantibodies." (PMID 23710207, 2013). "This review discusses the role of CUZD1 in cancer and autoimmunity." (PMID 23710207, 2013).
malignant brain tumors (1 paper, 2013). "The genomic structure of human CUZD1 is very similar to parts of the tumor suppressor DMBT1 (a gene deleted in malignant brain tumors) located at a locus exactly upstream of CUZD1 and in particular at 10q25.3–26.1." (PMID 23710207, 2013).
ovarian carcinoma (1 paper, 2013). A malignant neoplasm originating from the surface ovarian epithelium. "Elevated levels of CUZD1 were found in patients with ovarian cancer, but also in breast and lung cancer." (PMID 23710207, 2013). "mRNA overexpression of CUZD1 has been noted in ovarian cancer and serum levels of CUZD1 are elevated in women with ovarian cancer and patients suffering from pancreatic cancer." (PMID 23710207, 2013). "One key experiment that suggested an important role for CUZD1 in carcinogenesis demonstrated that human UO-44-specific antisera strikingly inhibit cell attachment and proliferation of NIH-OVCAR3 ovarian cancer cells." (PMID 23710207, 2013).
pancreatic cancer (1 paper, 2013). "The authors reported that CUZD1 is a novel pancreatic cancer serum biomarker as well, but they did not present data to support this statement." (PMID 23710207, 2013).
pancreatitis (1 paper, 2013). Inflammation of the pancreas. "In a murine model of necrotizing pancreatitis, UTCZP- (CUZD1-) deficient mice developed more severe pancreatitis suggesting that CUZD1 may play an important role in trypsinogen activation and in the severity of pancreatitis." (PMID 23710207, 2013).
primary sclerosing cholangitis (1 paper, 2018). "IgA type PABs were more prevalent in patients with primary sclerosing cholangitis (37.5% vs. 4.7% for anti-CUZD1 and 12.5% vs. 0% for anti-GP2, p<0." (PMID 29590158, 2018).
type I diabetes (1 paper, 2024). "In recent years, various antigens have been used to target pancreatic cells in type I diabetes, antigens such as insulin protein, CUZD1, ZNT8, GLUT1, etc48,49." (PMID 38355744, 2024).
ulcerative colitis (1 paper, 2013). An inflammatory bowel disease involving the mucosal surface of the large intestine and rectum. "The unexpectedly high prevalence of anti-CUZD1 and anti-GP2 antibodies in patients with ulcerative colitis warrants further investigations, as PABs are only found in less than 8% of patients with this disease." (PMID 23710207, 2013). "These authors did not provide data for individual reactivity to CUZD1 and GP2, but their overall data indicated the presence of PABs against the two antigens in 35.9% of patients with CD, 24.5% of patients with ulcerative colitis, and in none of the pediatric controls." (PMID 23710207, 2013).
cancer (3 papers, 2013 to 2025). A tumor composed of atypical neoplastic, often pleomorphic cells that invade other tissues. "Human CUZD1 is mapped at chromosome 10q26.13 and the loss of this region is a frequent event in various malignant tumours." (PMID 23710207, 2013). "However, this study was conducted in a very small number of sera and the diagnostic significance of CUZD1 as a cancer serum biomarker remains to be assessed in larger cohorts." (PMID 23710207, 2013). "In this review, we discuss the clinical significance of CUZD1, a novel biomarker with a dual role as a cancer and an autoantibody marker." (PMID 23710207, 2013). "CUZD1 is a pancreatic antigen with a dual role, as a cancer biomarker and an autoantibody target." (PMID 23710207, 2013). "For example, the commercial enzyme-linked immunosorbent assay (ELISA) for the pancreatic biomarkers, zona pellucida-like domains protein 1 (CUZD1), has been found to mistakenly recognize CA125, a known cancer antigen, which is nonhomologous to its intended target." (PMID 40056450, 2025).
CUZD1 also shares sentences with these, for which no sentence is quoted: breast carcinoma (2 papers); colorectal carcinoma (1); migraine (1).